CXCR4 (C-X-C motif chemokine receptor 4)
Diseases named in the same sentence as CXCR4 in open-access papers (continued):
Sharing a sentence is not in itself a finding about the gene and the disease.
medulloblastoma (26 papers, 2009 to 2024). A malignant, invasive embryonal neoplasm arising from the cerebellum. "Medulloblastoma development is suppressed when C-X-C motif chemokine receptor 4 (CXCR4) activity is restricted, which increases cAMP production comparable to phosphodiesterase blocking." (PMID 35805104, 2022). "The signaling pathways associated with phospholipase C, ILK1/integrin, CXCR4, Rho GTPase signaling, and actin nucleation are altered by SETD8 depletion in medulloblastoma." (PMID 36358786, 2022). "A subtype of medulloblastoma, pediatric brain tumors, are characterized by high expression of the chemokine receptor CXCR4 and concordant suppression of PPP2R2C." (PMID 33585078, 2021). "Previous reports described a functional crosstalk between PDGFR and CXCR4 signaling, as activation of PDGFR signaling promotes stability and phosphorylation of CXCR4 in medulloblastoma cells, inducing SDF-1/CXCR4 signaling." (PMID 30874597, 2019). "We showed a requirement for CXCR4 signaling in medulloblastoma xenografts using a clinically approved inhibitor, AMD3100 (Plerixafor/Mozobil®, Genzyme) which blocked in vivo growth of tumors." (PMID 26258793, 2015). "Compound screens have successfully identified compounds that activate Gs-associated GPCRs, resulting in inhibition of Shh signaling downstream of Gli1 and antagonists of the Gi-coupled receptor CXCR4 have demonstrated efficacy in medulloblastoma models." (PMID 26258793, 2015). "In fact, we have shown that CXCR4 inhibition has an anti-proliferative effect on Shh-driven medulloblastoma tumors in vivo, through downmodulation of cyclin D1 expression." (PMID 26258793, 2015). "Interestingly, double knock down of CXCR4 + CCR5 was more effective in decreasing the migration of hAT-MSCs toward medulloblastoma-BTICs or AT/RT-BTICs." (PMID 26076490, 2015). "Shh-driven medulloblastoma also exhibits the highest levels of CXCR4 gene expression, indicating that Shh-induced tumorigenesis may upregulate CXCR4 expression." (PMID 26258793, 2015). "Levels of CXCR4 expression identify two subgroups within the SHH subtype of medulloblastoma." (PMID 26283963, 2015). "Overall, inhibition PDGFA, CXCR4, BOC, MET, and NGFR have all shown therapeutic promise in SHH-subgroup medulloblastoma." (PMID 34667228, 2021). "MSCs have been show to upregulate tumor growth by migrating to the developing intrahepatic cholangiocarcinoma via SDF-1/CXCR4 signaling pathway, and MMP2 molecular factor in human medulloblastoma." (PMID 30513684, 2018). "A recent research article demonstrated that crosstalk among Wip1, CXCR4 and GRK5 promote aggressive phenotype of a medulloblastoma in children." (PMID 28915621, 2017). "When hAT-MSCs were co-cultured with medulloblastoma-BTICs, the expression levels of CCR4, CCR5, CCR7, XCR1, CXCR1, CXCR4, PDGFR-bb, KDR and TEK were increased, while the levels of CX3CR1, IL1R, IL6R, IL8R, IGF1R and CD44 were decreased (p<0.05)." (PMID 26076490, 2015). "Maximal tumor growth in murine and human models of SHH subtype medulloblastoma is dependent upon co-activation of SHH and the CXCR4 pathway." (PMID 26283963, 2015). "ERK1/2 activation in medulloblastomas can occur following activation of growth factor receptors, such as EGFR, PDGFR, IGF1R and CXCR4." (PMID 19594892, 2009). "AMD3100, AMD3465, and POL5551, also CXCR4 antagonists, have all been shown to block intracranial brain tumor growth in several experimental models, and this activity was correlated with the elevation of cAMP levels in models of GBM and medulloblastoma." (PMID 26283963, 2015). "Blockade of CXCR4 signaling, and elevation of cAMP levels, with specific small molecule antagonists has potent anti-tumor effects in intracranial xenograft models of SHH driven medulloblastoma." (PMID 26283963, 2015).
prostate tumor (26 papers, 2009 to 2024). "Among PC patients, higher expression of CXCR4 was documented in prostate tumor tissues from African Americans, suggesting aggressive phenotypes often associated with higher CXCR4 expression." (PMID 27809841, 2016). "Human prostate tumor expression of CXCR4 is also associate with poor survival, as its expression is significantly associated with local recurrence after therapy and formation of distant metastases." (PMID 23902739, 2013). "Among PC patients, higher expression of CXCR4 was documented in prostate tumor tissues from African American patients, suggesting CXCR4 expression is associated with aggressive disease phenotypes in these patients." (PMID 23902739, 2013). "The chemokine receptor CXCR4 is an important mediator of the interaction of prostate tumor cells with extracellular matrix proteins, supporting the invasion and migration of prostate tumor cells." (PMID 34073059, 2021). "Neutralization of CXCR4 with anti-CXCR4 antibodies reduced in vivo tumor growth and vascularization of CXCR4-overexpressing prostate tumors." (PMID 34503058, 2021). "CXCR4-deficient prostate tumors were significantly smaller and less invasive as compared to control tumors, confirming the role of the CXCL12-CXCR4 axis in initiating tumor formation." (PMID 31106200, 2019). "This suggests that in hormone-naïve patients with organ-confined prostate tumors with presumably normal circulating levels of androgens (e.g., ~10-34 nM testosterone), expression of the CXCR4 mRNA becomes de-repressed." (PMID 25884570, 2015). "In this study we detail how the synthetic androgen R1881 regulates the CXCR4/CXCR7 axis to control CXCL12-mediated motility of LNCaP prostate tumor cells." (PMID 25884570, 2015). "Androgens have been shown to increase the metastatic potential of prostate tumor cells by upregulating the expression of CXCR4." (PMID 25884570, 2015). "In vitro studies have recently shown that androgens regulate the expression of CXCR4 to increase the metastatic potential of prostate-tumor cells." (PMID 25884570, 2015). "To analyse the role of CXCR4 phosphorylation in our in vivo experiments, we used immunohistochemistry to measure the relative amounts of orthotopic prostate tumor cells positive for phosphorylated CXCR4." (PMID 26075720, 2015). "Taken together, these studies emphasize the clinical significance of CXCL12/CXCR4 expression in prostate tumor progression." (PMID 23902739, 2013). "As shown by microarray analysis and immunohistochemistry, murine epithelial cells from these PTEN-deficient prostate tumors display increased expression of CXCL12 and CXCR4 as compared to the normal prostate glands of PTEN+/+ and PTEN+/− mice." (PMID 23902739, 2013). "At the molecular level, CXCR4 is an important mediator of the interaction of prostate tumor cells with extracellular matrix proteins such as laminin, fibronectin, and collagen which contributes to the metastatic process." (PMID 22359577, 2012). "To confirm the role of CCL20 in the development and progression of CXCR4-overexpressing prostate tumors, we evaluated the effect of neutralizing antibodies to human CCL20 on the growth of CXCR4-overexpressing PC3 cells." (PMID 19340288, 2009). "Interestingly, CXCR4 is found on the surface of prostatic tumors cells, and its expression progressively correlates with the malignant degree, peaking in bone metastasis specimens." (PMID 35177982, 2021). "This suggests that CXCR4 expression is antagonized under homeostatic conditions and in the presence of circulating androgens, but that this suppression is relieved in hormone-naïve organ-confined prostate tumor cells." (PMID 25884570, 2015). "The AMP treatment also reduced CXCR4 protein expression by 30% in prostate tumors (P<0.05)." (PMID 22693649, 2012).
prostate tumor (continued). "Furthermore, the treatment with anti-CCL20 antibodies inhibited the growth of CXCR4-expressing prostate tumors." (PMID 19340288, 2009). "We recently reported that a chemokine CXCL12, also known as stromal-cell derived factor 1 (SDF-1), signaling via receptors CXCR4 and CXCR7 and activating tumor cell growth and invasion pathways, is responsible for accelerated prostate tumor growth in obesity." (PMID 33753872, 2021). "We showed that TMPRSS2-ERG fusions regulate CXCR4 expression in prostate tumors; thus, androgen induced ERG expression transcriptionally regulates CXCR4 expression in PC cells." (PMID 27809841, 2016). "In this study we showed that the synthetic androgen R1881 reciprocally regulates CXCR4 and CXCR7 expression at the protein level in androgen-sensitive human LNCaP prostate tumor cells." (PMID 25884570, 2015). "Transcriptional upregulation of the chemokine receptor 4 gene (CXCR4) in organ-confined tumor cells that overexpress the ETS-related gene ERG (i.e., TMPRSS2-ERG fusion) increases the motility of prostate tumor cells in vitro." (PMID 25884570, 2015). "C-X-C chemokine receptor type 4 (CXCR4) is a downstream target of ERG, whose upregulation in prostate-tumor cells contributes to their migration from the prostate gland." (PMID 25884570, 2015). "In prostate tumour cell-lines, SDF-1 signalling up-regulates the expression of CXCR4 and other downstream targets of its signalling pathway." (PMID 25162584, 2014). "Seven transmembrane receptors have been shown to heterodimerize with ERBB family members and studies have demonstrated that the CXCR7 co-receptor CXCR4 interacts with EGFR in other types of cancer, like tumors of the prostate and bladder." (PMID 25168820, 2014). "To examine the role of CXCR4 in the cell adhesion and migration of prostate tumor initiating cells, we compared FACS sorted CD44+/CD133+/CXCR4+ cells with other populations in cell adhesion assays." (PMID 22359577, 2012). "AKT activation promotes prostate tumour growth and metastasis via CXCL12/CXCR4 signalling." (PMID 26871266, 2016). "Moreover, similar expression level of CXCR4 and CCL20 was observed on the majority of prostate tumor samples (38 out of 48 samples, 79.5%) (5B′)." (PMID 19340288, 2009). "In summary, our findings in androgen-sensitive prostate tumor cells reveal that androgens modulate cell motility in a dose-dependent manner in response to chemokine CXCL12, and that they do so by regulating the expression of chemokine receptors CXCR4 and CXCR7." (PMID 25884570, 2015).
thyroid cancer (26 papers, 2005 to 2025). "In the GWASLN6, thyroid cancer signalling, as well as the CXCR4, ILK, IL-8, IL-3 and the JAK/STAT signallings, were statistically enriched." (PMID 41520521, 2025). "Clinical studies have shown that CXCR4 expression is positively correlated with more invasive and poorly prognostic tumors in thyroid cancer." (PMID 41374320, 2025). "In contrast, thyroid cancer signalling, CXCR4, ILK, IL-8, IL-3, JAK/STAT and mTOR signalling pathways were significantly enriched in GWASLN6." (PMID 41520521, 2025). "On one hand, these agents are currently being explored for their efficacy in other tumor types; on the other hand, the molecular mechanisms of CXCR4 in thyroid cancer remain to be elucidated, necessitating further in-depth studies in the future." (PMID 41374320, 2025). "CXCR4 and SDF-1 are indicators of more aggressive papillary thyroid cancer types and act as key regulators of local and distant metastasis in various types of thyroid cancer, leading to a poorer prognosis in CXCR4/SDF-1-positive cancers." (PMID 36419107, 2022). "Pronounced intra-individual variability in SST and CXCR4 expression is well documented in the literature for many tumour entities and has also been noted for thyroid cancer." (PMID 35799158, 2022). "It was observed that high expression of CXCL12/CXCR4 and low density of CD8-positive T-lymphocytes are more likely to cause shorter overall survival in thyroid cancer." (PMID 36612163, 2022). "In thyroid cancer, the CXCR4/CXCR7/SDF-1 axis has been investigated gaining importance in the understanding of the progression of thyroid cancer and metastasis development." (PMID 36419107, 2022). "The aim of the present study was to comprehensively re-evaluate SST and CXCR4 expression in a large set of thyroid carcinoma samples of all four entities by immunohistochemistry using well-characterised rabbit monoclonal antibodies." (PMID 35799158, 2022). "Whereas no major differences in SST expression were noted between the four thyroid carcinoma entities, CXCR4 expression was significantly higher in highly malignant APC than in well-differentiated PTC and FTC." (PMID 35799158, 2022). "Recently, somatostatin receptors (SSTs) and the chemokine receptor CXCR4 have been evaluated for the treatment of thyroid carcinomas, however, with contradictory results." (PMID 35799158, 2022). "The CXCR4/RhoA signaling pathway participates in miR-128-modulated human thyroid carcinoma cells proliferation and apoptosis." (PMID 34322132, 2021). "Here, senescent cells enhanced anoikis resistance in thyroid cancer cell lines via CXCL12/CXCR4 signalling." (PMID 28489070, 2017). "Interestingly, in addition to the indirect mechanisms through CAFs, UA was shown to inhibit thyroid cancer progression by reducing the expression levels of both CXCR4 and CXCR7 mRNA and protein." (PMID 36077709, 2022). "Because a given receptor must display at least moderately strong expression intensity (i.e., IRS ≥6) to be clinically useful as a target structure, our results indicate that very few patients with thyroid cancer would likely benefit from SST- or CXCR4-based diagnostics or therapy." (PMID 35799158, 2022). "Accordingly, the results of the TCGA cohort demonstrated higher expression of CXCR4 and SDF-1 in classic papillary thyroid cancer, reflecting the relative importance of the CXCR4/SDF-1 interaction predominantly in this thyroid cancer histology compared with other thyroid cancer types." (PMID 36419107, 2022). "Several cancer types show a significant overexpression of CXCR4, including thyroid cancer." (PMID 36419107, 2022). "SST and CXCR4 expression levels are generally low in thyroid carcinomas." (PMID 35799158, 2022). "To determine whether senescent cells were capable of attracting cancer cells through the CXCL12/CXCR4 signalling, we performed an in vitro cell migration assay using two kinds of thyroid cancer cell lines: SNU790-CXCR4 and HTH83." (PMID 28489070, 2017).
thyroid cancer (continued). "The CXCL12/CXCR4/CXCR7 axis may contribute to thyroid cancer development by regulating cancer cell migration and invasion via AKT, ERK signaling and MMP-2 activation." (PMID 28272462, 2017). "CXCR4 has been observed to be upregulated in thyroid cancer." (PMID 24288553, 2013). "Therefore, targeting of tumour microvessels using anti-SST or anti-CXCR4 therapies might represent a promising (additional) therapeutic strategy for thyroid carcinomas." (PMID 35799158, 2022). "CXCL12 binds to CXCR4 and CXCR7 proteins on thyroid cancer cells and activates several signaling pathways such as mTOR, ERK1/2, SAPK/JNK, Akt, p38, and BTK." (PMID 40136652, 2025). "In conclusion, the presented study suggests that the prognostic significance of the combined high expression of CXCR4 and SDF-1 in differentiated thyroid cancer depends on the density of tumor-infiltrating CD8 positive T-lymphocytes." (PMID 36419107, 2022). "In particular, CXCL12 (also known as SDF-1) binds to CXCR4 and CXCR7 proteins on thyroid cancer cells and consequently activates multiple signaling pathways, including mTOR, ERK1/2, SAPK/JNK, Akt, p38 and BTK." (PMID 36077709, 2022). "In contrast to the majority of the existing data for SSTs and CXCR4, our investigations revealed low levels of SST and CXCR4 expression in thyroid carcinoma samples overall." (PMID 35799158, 2022). "Significant differences between the four thyroid carcinoma entities with regard to receptor expression were only observed for SST4 and CXCR4." (PMID 35799158, 2022). "miR-1 is able to inhibit thyroid carcinoma cell proliferation and migration by targeting CCND2, CXCR4 and CXCL12." (PMID 24079748, 2013). "It was recently reported that in advanced CD8 negative thyroid cancer, high expression of CXCR4 and its ligand CXCL12 (SDF-1) correlates with bad prognosis, thus contradicting to TCGA data." (PMID 37006265, 2023). "Based on these findings, further studies are needed to evaluate the prognostic significance of CXCR4/SDF-1 in relation to CD8+ density in different cancers with known prognostic influence of the CXCR4/SDF-1 axis alone, including different types of thyroid cancer." (PMID 36419107, 2022). "There are other studies that regulate thyroid cancer with similar signaling pathways, such as lncRNA DUXAP8 promotes the cell proliferation, migration, and invasion of papillary thyroid carcinoma via miR-223-3p mediated regulation of CXCR4." (PMID 35264071, 2022). "CXCR4-based diagnostics and therapies have not yet been undertaken in thyroid carcinomas, which also indirectly supports our (largely negative) results." (PMID 35799158, 2022). "The expression of CXCL12, CXCR4, and CXCR7 was detected in thyroid cancer tissue specimens." (PMID 29977225, 2018). "Therefore, therapies targeting the CXCL12/CXCR4/CXCR7 axis could be a promising and effective therapeutic strategy for thyroid cancer." (PMID 40136652, 2025). "SST- or CXCR4-based diagnostics or therapy in thyroid carcinomas should not be considered in general but may be feasible in single cases with high levels of expression of these receptors." (PMID 35799158, 2022). "We found that patients expressing high levels of CXCR4 have high levels of LPA1 in breast, pancreatic, and thyroid cancers, suggesting that the lack of correlation between CXCR4 expression and patient survival may be due to CXCR4 inhibition by the LPA1/LPA axis." (PMID 37749552, 2023). "Therefore, SST- or CXCR4-based diagnostics or therapy in thyroid carcinomas should not be considered in general, although they might be feasible in single cases with high expression of these receptors." (PMID 35799158, 2022). "Second, due to the fact that differentiated thyroid cancer harbors an excellent prognosis compared to other cancers and the small number of cancer specimen in our TMA cohort, we were not able to evaluate the prognostic relevance of CXCR4, pCXCR4, SDF-1 and CD8+ in this cohort." (PMID 36419107, 2022).